USP21 (ubiquitin specific peptidase 21)
Diseases named in the same sentence as USP21 in open-access papers (continued):
Sharing a sentence is not in itself a finding about the gene and the disease.
asthma (4 papers, 2015 to 2022). "Increased expression of USP21 has been found in Treg cells of asthma patients; the imbalance of FOXP3 and GATA3 is an important cause of pathogenic alteration of Treg cells in asthma patients." (PMID 35846989, 2022). "Most importantly, the mRNA levels of USP21 and PIM2 were upregulated in the Treg cells of asthma patients." (PMID 30013989, 2018). "Overexpression of USP21 can rescue GATA3 from its degradation so as to stabilize the expression of GATA3; RT-PCR showed that the mRNA of USP21 is upregulated in the Treg cells of asthma patients." (PMID 30013989, 2018). "Previous studies showed that both USP21 and PIM2 are regulators of GATA3 and FOXP3 expression, respectively, in Treg cells, so we measured the expressions of USP21 and PIM2 in Treg cells from patients with asthma and healthy subjects." (PMID 30013989, 2018). "We thought the explanation was that USP21 or PIM2 may regulate the expression in a complicated way rather than in a linear relationship and it is possible that other molecules participate in the regulation of Treg cells in the pathogen of asthma." (PMID 30013989, 2018).
oral squamous cell carcinoma (4 papers, 2020 to 2022). "In contrast, FDG5-AS1 and SNHG16 function as miRNA sponges for miR-520b and miR-4500, leading to increased expression of USP21 in oral squamous cell carcinoma and NSCLC, respectively." (PMID 35846989, 2022). "miR-520b/USP21 is involved in lncRNA FGD5-AS1-enhanced oral squamous cell carcinoma." (PMID 33758783, 2021).
colon cancer (3 papers, 2020 to 2024). "USP21-KO colon cancer cells exhibited significantly reduced proliferation, migration, colony formation, and 3D tumor spheroid formation in response to EGF." (PMID 39695128, 2024). "Validation in 41 pairs of colon cancer samples from the TCGA-COAD cohort confirmed a pronounced elevation of USP21 expression specifically in CRC." (PMID 38834869, 2024). "We found that ubiquitin-specific protease 21 (USP21) increases Fra-1 stability by deubiquitinating Fra-1 and enhances the expression of Fra-1 target genes in colon cancer cells." (PMID 31947604, 2020). "Based on this result, this study confirmed that USP21 is required for protein stability of Fra-1 in colon cancer cells." (PMID 31947604, 2020). "First, we determined the effect of USP21 on stabilizing Fra-1 under USP21 knockdown conditions in two colon cancer cell lines, HCT116 and HT-29." (PMID 31947604, 2020). "We therefore evaluated the effect of USP21 on both migration and invasion activities in colon cancer cells, HCT116 and HT29." (PMID 31947604, 2020). "We examined the effects of USP21 on Fra-1-dependent AP-1 transcriptional activity using luciferase reporters in colon cancer cells." (PMID 31947604, 2020). "Since this study showed that USP21 was associated with enhanced migration and invasion activities in colon cancer, we tested the effect of USP21 on the metastatic ability of cancer cells in a mouse model." (PMID 31947604, 2020). "Furthermore, the tumorigenic activity in vivo was markedly diminished in NSG mice xenografted with USP21-KO colon cancer cells." (PMID 39695128, 2024). "We assessed the ability of USP21-KO cells to promote colon cancer progression upon exposure to EGF." (PMID 39695128, 2024). "Our results obtained from molecular and cell biology experiments as well as immunohistochemical assessment of human patient samples were consistent with our mouse model results, namely that USP21 knockdown in colon cancer cells showed reduced metastatic activity." (PMID 31947604, 2020). "To validate this hypothesis, we screened DUBs that ubiquitin-dependently control Fra-1 stability, identified USP21 as a Fra-1 DUB, and confirmed that USP21 overexpression enhances the MMP-1 gene expression transcribed by Fra-1 in colon cancer cells." (PMID 31947604, 2020). "Importantly, xenograft assays revealed a significant reduction in tumor growth and size in NSG mice implanted with USP21-KO HCT-15 cells compared to those implanted with Ctrl HCT-15 cells, strongly indicating the critical role of USP21 in the tumorigenicity of colon cancer cells." (PMID 39695128, 2024). "Our results demonstrate that USP21 enhances EGFR expression by stabilizing the receptor through deubiquitination, thus promoting EGFR-mediated signaling in colon cancer cells." (PMID 39695128, 2024). "Based on our biochemical findings, we investigated the role of USP21 in CRC progression through both in vitro and in vivo assays using USP21-KO colon cancer cells." (PMID 39695128, 2024). "To ensure that these findings held true for colon cancer cells (HCT116), we investigated the effect of USP21 on Fra-1 activity by measuring the expression of MMP-1, a target gene of Fra-1 as AP-1 binds to the MMP-1 promoter." (PMID 31947604, 2020).
glioblastoma (3 papers, 2022 to 2024). The most malignant astrocytic tumor (WHO grade IV). "USP21 promotes self-renewal and tumorigenicity of mesenchymal glioblastoma stem cells by deubiquitinating and stabilizing FOXD1." (PMID 38829550, 2024).
liver cancer (3 papers, 2017 to 2024). An epithelial or non-epithelial malignant neoplasm that arises from the liver. "The results revealed that the expression of HSP90AA1, PPIA, SQSTM1, and USP21 was significantly increased in liver cancer tissues compared with normal liver tissues (p < 0.05), which was consistent with the results of the bioinformatics analysis." (PMID 36795724, 2023).
pancreatic ductal adenocarcinoma (3 papers, 2020 to 2024). An infiltrating adenocarcinoma that arises from the epithelial cells of the pancreas. "In human pancreatic ductal adenocarcinoma, USP21 activated the Wnt pathway to promote the stemness of cancer cells by acting as a deubiquitinase of TCF7." (PMID 38906857, 2024). "In addition, USP21 amplification/ overexpression was positively correlated with human pancreatic ductal adenocarcinoma disease progression." (PMID 32784507, 2020).
prostate carcinoma (3 papers, 2017 to 2021). A carcinoma that arises from epithelial cells of the prostate gland. "We showed that USP21 is also amplified in prostate cancer CTCs." (PMID 32784507, 2020).
renal carcinoma (3 papers, 2016 to 2018). A carcinoma arising from the epithelium of the renal parenchyma or the renal pelvis. "On the other hand, USP21 also mediates transcriptional initiation of IL8 leading to an expansion of the stem cell pool in renal carcinoma cells." (PMID 29706623, 2018). "In renal carcinoma cells, USP21 has been reported to deubiquitinate microtubule affinity-regulating kinase (MARK) proteins, which further promote the well-known Hippo pathway." (PMID 29706623, 2018). "To further confirm the effects of USP21 in renal cancer cells, we used A-704 cell line for its functional study." (PMID 27259257, 2016).
Splenomegaly (3 papers, 2016 to 2021). Abnormal increased size of the spleen. "They found that elderly USP21 knockout mice exhibited spontaneous T cell activation and splenomegaly." (PMID 33628844, 2021). "Recently, two independent studies showed that the USP21 knockout mice were viable and fertile, spontaneously developed splenomegaly and were more resistant to vesicular stomatitis virus infection with elevated production of interferons." (PMID 29263902, 2016).
viral infections (3 papers, 2021 to 2023). "Collectively, these studies suggested a dual role for USP21 in anti-viral infections." (PMID 35846989, 2022). "Hence, at late stages of viral infection, p38-mediated phosphorylation of USP21 (Ubiquitin Specific Peptidase 21), a deubiquitinating enzyme, inhibits STING." (PMID 33922633, 2021). "In addition, USP21 depletion contributed to the significant production of IFNs by activating the RIG-I or STING pathway, raising the possibility that USP21 inhibitors may enhance immune responses against virus infection." (PMID 35846989, 2022).
Cirrhosis (2 papers, 2019 to 2022). A chronic disorder of the liver in which liver tissue becomes scarred and is partially replaced by regenerative nodules and fibrotic tissue resulting in loss of liver function. "In line with the significant role of USP21 in HCC, the variation score of a 20 gene-based gene set including USP21 may reflect the pathological progression from cirrhosis to HCC and serve as an independent prognostic factor for recurrence-free and overall survival." (PMID 35846989, 2022).
esophageal cancer (2 papers, 2024). A primary or metastatic malignant neoplasm involving the esophagus. "Upon preparing this manuscript, one recent study reported that USP21 promotes proliferation and glycolysis of esophageal cancer cells, however, whether the oncogenic role of USP21 depends on its deubiquitinase activity or not remains unknown." (PMID 38906857, 2024).
Hepatic fibrosis (2 papers, 2021 to 2022). The presence of excessive fibrous connective tissue in the liver. "An additional study uncovered the multifaceted effects of USP21 in Treg cell-mediated regulation of immune interactions between Schistosoma and its host, suggesting the potential role of USP21 in regulating liver fibrosis in patients with schistosomiasis." (PMID 35846989, 2022). "In the WT mice, liver inflammation and liver fibrosis were more serious, and the number of parasites recovered from tissues and cells was increased, and the hepatocyte activity and USP21 expression were increased." (PMID 33628844, 2021). "USP21 may have potential for regulating hepatic fibrosis in patients with schistosomiasis." (PMID 33628844, 2021).
Hyperglycemia (2 papers, 2023 to 2025). An increased concentration of glucose in the blood. "In skeletal muscle-specific whole-body (KO) of USP21 the hyperglycemia induced by high-fat feeding for 9 weeks was significantly attenuated, while insulin sensitivity was improved." (PMID 40806701, 2025). "USP22 in pancreatic β-cells, USP2 in adipose tissue macrophages, USP9X, 20, and 33 in myocytes, USP4, 7, 10, and 18 in hepatocytes, and USP2 in hypothalamus improve hyperglycemia, whereas USP19 in adipocytes, USP21 in myocytes, and USP2, 14, and 20 in hepatocytes promote hyperglycemia." (PMID 36834633, 2023).
lung squamous cell carcinoma (2 papers, 2020 to 2022). "To understand the role of DUBs in NSCLCs, we analyzed the expression levels of USP21 in LC patients using the lung adenocarcinoma (LUAD) and lung squamous cell carcinoma (LUSC) data set of The Cancer Genome Atlas (TCGA)." (PMID 31956270, 2020).
Obesity (2 papers, 2024 to 2025). Accumulation of substantial excess body fat. "Thus, an important risk for type 2 DM represented by obesity might be modulated by genetic USP21 ablation in skeletal muscle." (PMID 40806701, 2025). "Altering the expression levels of USP21 and USP9X have therefore been suggested to have therapeutic potential in the treatment of obesity and impaired insulin sensitivity, which are both associated with muscle physiology." (PMID 38716888, 2024). "Removal of USP21 resulted in an increased mitochondrial activity in skeletal muscle, leading to promotion of an oxidative myofiber phenotype, and inhibition of obesity and type 2 diabetes." (PMID 38716888, 2024). "Similarly, in skeletal muscles, USP21 is up-regulated in individuals with obesity, and correlates with fasting glucose levels in animals on a high-fat diet." (PMID 38716888, 2024).
ovarian tumor (2 papers, 2014 to 2023). "Furthermore, a co-IP assay between USP21 and deletion forms of YOD1 revealed that the ubiquitin regulatory X (UBX), ovarian tumor (OTU) domain of YOD1 are required for the interaction between USP21." (PMID 37743467, 2023).
papillary thyroid carcinoma (2 papers, 2022 to 2026). "In papillary thyroid carcinoma, SNHG5 binds and stabilizes RBM47, preventing ubiquitin-mediated degradation of FOXO3 via recruitment of USP21." (PMID 41550840, 2026). "A recent study showed that RBM47 inhibited proliferation in papillary thyroid carcinoma by stabilizing the lncRNA SNHG5, which in turn acted as a scaffold, binding with USP21 to regulate the expression of FOXO3, implying that USP21 is required for the tumor-suppressive role of RBM47." (PMID 35846989, 2022).
schistosomiasis (2 papers, 2021 to 2022). An infectious disease caused by parasitic trematodes of the genus Schistosoma that colonize human blood vessels and release eggs that can cause granulomatous reactions leading to acute (swimmer's itch or acute schistosomiasis syndrome) or chronic disease. "Based on this finding, USP21-deficient Tregs increased the susceptibility of mice to schistosomiasis." (PMID 33628844, 2021).
triple-negative breast carcinoma (2 papers, 2022 to 2024). An invasive breast carcinoma which is negative for expression of estrogen receptor (ER), progesterone receptor (PR), and human epidermal growth factor receptor 2 (HER2). "Recent studies revealed that USP21 affects JAK2/STAT3 axis in triple-negative breast cancer by indirect regulation of JAK2 stability." (PMID 39305962, 2024).
adenoma (1 paper, 2020). A neoplasm arising from the epithelium. "USP21 expression was found to be significantly enhanced in colorectal adenocarcinoma cells compared to normal cells and adenoma cells." (PMID 31947604, 2020).
alcoholism (1 paper, 2022). "A recent study has shown that disulfiram, a clinically used anti-alcoholism drug, could function as a potent inhibitor of USP21." (PMID 35974001, 2022).
breast tumour (1 paper, 2016). "In this context, it is interesting to note that USP21 has been identified in a large-scale screen as one of only few genes that has a significantly increased copy number count in breast tumour samples." (PMID 27621083, 2016).
cervical cancer (1 paper, 2024). A primary or metastatic malignant neoplasm involving the cervix. "For example, ubiquitin-specific peptidase 21 can activate YAP via controlling FOXM1 stability, blocking Hippo signaling, lowering cell proliferation, causing apoptosis, and eventually increasing the radiosensitivity of cervical cancer cells." (PMID 39187525, 2024).
clear cell carcinoma (1 paper, 2016). "We found that, compared with HEK293T cells, USP21 mRNA was expressed at higher levels in all RCC cell lines, including three adenocarcinoma lines 786-O, 789-P and A-704, two clear cell carcinoma Caki-1 and Caki-2." (PMID 27259257, 2016).
COVID-19 (1 paper, 2023). A disease caused by infection with severe acute respiratory syndrome coronavirus 2. "In contrast to COVID-19(+) TV, highly expressed in the COVID-19(-) PU control group included MHC class II antigen processing (HLA-DRB3/4, HLA-DPB1, HLA-DRA, CIITA, and CD74), mast cell degranulation (TPSAB1/B2), B cell activation (CXCL13, BLNK, IL-6) and histone modification (USP21, HIST1H4E)." (PMID 37026002, 2023).
diffuse large B-cell lymphoma (1 paper, 2022). "By maintaining EZH2 protein levels, USP21 promotes cell proliferation and metastasis in bladder carcinoma and cell proliferation in diffuse large B-cell lymphoma." (PMID 35846989, 2022).
embryonic carcinoma (1 paper, 2016). "Importantly, endogenous Nanog physiologically interacted with endogenous USP21 in mESCs (E14) and human embryonic carcinoma NCCIT cells." (PMID 29263902, 2016).
glioma (1 paper, 2022). A benign or malignant brain and spinal cord tumor that arises from glial cells (astrocytes, oligodendrocytes, ependymal cells). "Furthermore, miR-637 inhibited cancer cell invasion in glioma and HCC by targeting CDK6 and USP21, respectively." (PMID 36175921, 2022). "These miR-637-targeted genes include HMGA1, CDK6, and WNT7A in glioma, HEMGN in PTC, APLN in GC, USP21 in HCC, LY6E and CTSB in CHOL, NUPR1 in OSCC and MM, HDAC4 in SaOS, ABL1 in CML, KLK4 in OC, PLXNB2 in OC, AKT1 in TNBC, PTC, and HCC, AKT3 in TNBC, and RING1 in CCa." (PMID 36175921, 2022).
hydatidiform mole (1 paper, 2022). A gestational trophoblastic disorder characterized by marked enlargement of the chorionic villi, hyperplasia of the villous trophoblastic cells and hydropic changes. "Higher expression of USP21 and Nanog was detected in androgenetic complete hydatidiform moles (CHMs) with a 46, XX karyotype than in normal villi, suggesting that the USP21-Nanog pathway may participate in the disruption of XCI in androgenetic CHM." (PMID 35846989, 2022).
lymphoma (1 paper, 2024). A malignant (clonal) proliferation of B- lymphocytes or T- lymphocytes which involves the lymph nodes, bone marrow and/or extranodal sites. "In addition, USP21 participates in the development of lymphoma through the stabilization of enhancer of zeste homolog 2 (EZH2), which is required for generating germinal centers and lymphoma tumors." (PMID 39664521, 2024).
metastatic cancers (1 paper, 2020). A carcinoma which has spread from the original site of growth to another anatomic site. "Furthermore, considering the roles of USP21 and Fra-1 and their abundance in other cancers, USP21 can be considered a potential biomarker and a therapeutic target for various metastatic cancers." (PMID 31947604, 2020).
renal clear cell carcinoma (1 paper, 2017). "USP21 protein was expressed at low levels in a majority of renal clear cell carcinoma (RCC) samples, suggesting that low USP21 activity could increase cancer relevant cellular phenotypes." (PMID 28969054, 2017). "Low expression of USP21 in early stage renal clear cell carcinoma suggests that USP21 may be a useful biomarker." (PMID 28969054, 2017).
sarcopenia (1 paper, 2025). Progressive decline in muscle mass due to aging which results in decreased functional capacity of muscles. "In addition, several therapeutic approaches proved to be promising interventions for slowing the progression of sarcopenia in DM, including physical activity, newer antihyperglycemic classes, D-pinitol, and genetic USP21 ablation, although none of them were yet validated for clinical use." (PMID 40806701, 2025).
Stroke (1 paper, 2024). Sudden impairment of blood flow to a part of the brain due to occlusion or rupture of an artery to the brain. "USP21 also regulates protein stability and stem cell pluripotency, is dysregulated in models of stroke, and exerts oncogenic functions." (PMID 39335533, 2024).
thyroid cancer (1 paper, 2025). "In summary, SNHG5 is universally underexpressed in thyroid cancer and exerts tumor-suppressive effects through the RBM47/USP21/FOXO3 pathway and miR-510-5p-related mechanisms." (PMID 41234719, 2025).